HS1BP3 (HCLS1 binding protein 3)
Description:
May be a modulator of IL-2 signaling.
Synonyms: HS1-BP3; FLJ14249; ETM2
Tractability: PROTAC: ubiquitination databases record sites on it; its protein half-life has been measured.
Gene: Protein-coding gene on chromosome 2 (20,560,448 to 20,651,152, reverse strand). Ensembl gene ENSG00000118960.
Subcellular location (Human Protein Atlas): Nucleoli; Cytosol
Gene Ontology:
Molecular function: protein binding; phosphatidylinositol binding
Biological process: regulation of apoptotic process
Cellular component: endoplasmic reticulum; mitochondrion
Genetic constraint (gnomAD): Loss-of-function variants: 28 observed, 31.67 expected, observed/expected ratio (o/e) 0.88, 90% interval 0.65 to 1.21. The upper end of that interval is the gene's LOEUF score, 1.21, which puts it in group 5 of 6, group 1 being the genes least tolerant of losing a copy. Missense variants: 470 observed, 497.44 expected, observed/expected ratio (o/e) 0.94, 90% interval 0.88 to 1.02. Synonymous variants: 184 observed, 209.19 expected, observed/expected ratio (o/e) 0.88, 90% interval 0.78 to 0.99.
Homologues: Orthologues: chimpanzee HS1BP3 (98% identical), macaque HS1BP3 (93% identical), rabbit HS1BP3 (82% identical), dog HS1BP3 (80% identical), pig HS1BP3 (80% identical), rat Hs1bp3 (78% identical), guinea pig HS1BP3 (78% identical), mouse Hs1bp3 (77% identical), tropical clawed frog hs1bp3 (45% identical), zebrafish hs1bp3 (35% identical).
Diseases named in the same sentence as HS1BP3 in open-access papers:
HS1BP3 is named in the same sentence as 12 diseases in open-access papers, as found by Europe PMC text mining. Sharing a sentence is not in itself a finding about the gene and the disease. The quoted sentences say what the papers report.
essential tremor (5 papers, 2018 to 2025). A relatively common disorder characterized by a fairly specific pattern of tremors which are most prominent in the upper extremities and neck, inducing titubations of the head. "Of note, a different variant in HS1BP3 (p.A265G) was previously associated with essential tremor (ET), a disorder potentially related to the adult‐onset dystonias through common genetics." (PMID 29770609, 2018). "Genetically, the HS1BP3 gene, which encodes HS1-binding protein 3, is one of candidate genes for familial essential tremor and highly expressed in motor neurons and Purkinje cells regulating Ca2+-dependent protein kinase activation of tyrosine and tryptophan hydroxylase." (PMID 32982923, 2020). "ENSA has been shown to interfere with SNCA self-assembly and thereby alleviate its neurotoxicity, and variants in HCLS1 binding protein 3 were found to be associated with the related condition of essential tremor (but not PD itself)." (PMID 39711708, 2025).
blepharospasm (1 paper, 2019). "Interestingly, a recent study showed that deleterious variants in CACNA1A, REEP4, TOR2A, ATP2A3, HS1BP3, GNA14, and DNAH17 were involved in blepharospasm, and none of these variants except for CACNA1A has been reported to be associated with blepharospasm." (PMID 32038460, 2019).
cervical dystonia (1 paper, 2018). "Deleterious variants in HS1BP3 (NM_022460.3: c.94C>A, p.Gly32Cys) and GNA14 (NM_004297.3: c.989_990del, p.Thr330ArgfsTer67) were identified in a father and son with segmental cranio‐cervical dystonia first manifest as BSP." (PMID 29770609, 2018).
Dystonia (1 paper, 2018). An abnormally increased muscular tone that causes fixed abnormal postures. "A small pedigree with BSP+ and Parkinsonism harboring variants in HS1BP3 and GNA14 highlights the distinct possibility of oligogenic inheritance in BSP and other anatomical distributions of dystonia." (PMID 29770609, 2018).
gastric adenocarcinoma (1 paper, 2026). "Here, we demonstrate that high expression of HS1BP3 is associated with reduced survival for gastric adenocarcinoma and triple negative breast carcinoma patients and that HS1BP3 is specifically upregulated in these cancers." (PMID 41960636, 2026).
cancer (1 paper, 2026). A tumor composed of atypical neoplastic, often pleomorphic cells that invade other tissues. "The HCLS1-Binding Protein 3 (HS1BP3) interacts with the SH3 domain of cortactin (CTTN), a protein that contributes to a malignant phenotype in cancers." (PMID 41960636, 2026). "We mapped the HS1BP3-cortactin interaction site to the third proline-rich region (PRR3.1) of HS1BP3 and show that this interaction is important for cancer cell proliferation, extracellular matrix degradation and secretion." (PMID 41960636, 2026).
HS1BP3 also shares sentences with these, for which no sentence is quoted: hepatocellular carcinoma (1 paper); mesothelioma (1); Onset (1); Parkinsonism (1); triple-negative breast carcinoma (1); tumor (1).